JAK2 (Janus kinase 2)
Diseases named in the same sentence as JAK2 in open-access papers (continued):
Sharing a sentence is not in itself a finding about the gene and the disease.
essential thrombocythemia (continued). "The reported prevalence of the JAK2 mutation has ranged from 65%-97% in polycythemia vera (PV) patients from Europe and North America, 23%-57% in patients with essential thrombocythemia (ET), and 35%-57% in primary myelofibrosis (PMF) patients." (PMID 33507708, 2021). "A hypercoagulable state occurs in essential thrombocytosis because of the overproduction of hematopoietic cells secondary to the mutation of the JAK2, CALR, or MPL genes." (PMID 34845429, 2021). "Although the number of mutations causing primary thrombocytosis has recently increased, a stepwise approach first targeting the three hot-spot genes JAK2, MPL, and CALR besides screening for BCR-ABL1 seems to be justified." (PMID 33712866, 2021). "In 2005 four groups including that of Tony Green in Cambridge described the JAK2 V617F mutation in most patients with polycythaemia vera and about half those with essential thrombocythaemia (ET) and myelofibrosis (MF) (reviewed by Campbell and Green)." (PMID 35844697, 2021). "Chronic myeloid leukemia (CML) is characterized by the BCR–ABL1 fusion gene mutation whereas polycythemia vera (PV), essential thrombocythemia (ET) and myelofibrosis (MF) are typically characterized by the presence of JAK2, CALR, or MPL gene mutations." (PMID 33923680, 2021). "In 2013, somatic CALR mutations were identified in most JAK2-unmutated patients with Essential Thrombocythemia (ET) or Primary Myelofibrosis (PMF) patients." (PMID 31332222, 2019). "The JAK2 V617F mutation is also detected in approximately 50–60% of patients with primary myelofibrosis (PMF) or essential thrombocythemia (ET)." (PMID 29641446, 2018). "The JAK2 V617F mutation is found rarely in aCML cases, while it is frequent in Polycythaemia Vera (PV), Essential Thrombocythemia (ET) and Myelofibrosis (MF)." (PMID 29455651, 2018). "Essential thrombocythemia (ET) is characterized in about half of the cases by the somatic mutation JAK2 V617F." (PMID 25525531, 2014). "A mutation in the gene encoding Janus kinase 2 (JAK2) is present in 50% of patients with essential thrombocytosis; however, it can be found in healthy individuals." (PMID 24829806, 2013). "The patient was diagnosed as SVT due to MPD (essential thrombocytosis, ET) with JAK2 V617F mutation." (PMID 23876158, 2013). "We report a case of postpartum recurrent non-ST elevation myocardial infarction in a 40-year-old caucasian woman with essential thrombocythaemia in the presence of a positive JAK-2 mutation and an elevated anti-cardiolipin IgM antibody titer." (PMID 20565738, 2010). "Her past medical history was significant only for the diagnosis of essential thrombocythemia (ET) based on a bone marrow biopsy and a positive JAK2 mutation test." (PMID 20181185, 2009). "Approximately 60% of patients with essential thrombocythemia express the JAK2 V617F mutation." (PMID 40926892, 2025). "Moreover, the JAK2 V617F mutation was detected in over 50% of individuals diagnosed with essential thrombocythemia (ET)." (PMID 38273387, 2024). "Furthermore, when polycythemia and/or essential thrombocytosis coincide with HE, testing for the JAK2 V617F mutation, CALR, and MPL mutations is recommended." (PMID 39056762, 2024). "Essential thrombocythemia (ET) is a blood cancer caused by mutations in JAK2 and CALR." (PMID 38672593, 2024). "In Essential thrombocythemia (ET), persistent elevated platelet counts and megakaryocytic proliferation in the marrow are hallmark features with nearly 55% of patients harboring the JAK2 V617F mutation." (PMID 34804065, 2021). "Bone marrow biopsy confirmed JAK2-mutation-positive essential thrombocytosis." (PMID 33505762, 2020). "For instance, detecting BCR-ABL1 transcript, the causative agent of rare chronic myeloid leukemia mimicking essential thrombocytemia (ET), and JAK2, CALR, MPL mutations, which are present in three myeloproliferative neoplasms: ET, primary myelofibrosis, and polycythemia vera." (PMID 32188124, 2020).
essential thrombocythemia (continued). "We therefore assessed the ex vivo effects of INCB053914 on neoplastic erythroid colony formation in primary cell cultures obtained from patients with polycythemia vera (PV), essential thrombocythemia (ET), and primary myelofibrosis (MF) who possess the activating JAK2 V617F mutation." (PMID 29927999, 2018). "This case may be of interest because of the favourable outcome in spite of the large size of the PCFCL, the rare combination with essential thrombocythaemia and because it contributes to discussion on the role of JAK2 mutation in such patients." (PMID 24690328, 2014). "This case report may constitute further proof that in familial essential thrombocythemia there are other, still undefined, constitutional, inherited genetic factors predisposing to the acquisition of various somatic mutations (e.g., JAK2 V617F and MPL)." (PMID 25525531, 2014). "According to what has been proposed, CALR mutations could be used as a diagnostic tool in the same way JAK2 alterations have improved accuracy of current diagnosis of essential thrombocythemia and primary myelofibrosis." (PMID 25068507, 2014). "To date, several JAK2 single nucleotide polymorphisms (SNPs) have been identified that they were significantly associated with polycythemia vera (PV) and essential thrombocythemia (ET), including rs7046736, rs10815148, rs12342421, rs10758669, rs3808850 and rs10974947." (PMID 23717640, 2013). "A mutation in JAK2 kinase (V617F) was found to be associated with essential thrombocytosis." (PMID 22472269, 2012). "In the event of preexisting thrombocytosis, we tested the patient for positivity for the JAK2 V617F mutation to establish whether it was essential thrombocytosis according to the recently revised diagnostic criteria." (PMID 21569611, 2011). "Essential thrombocythemia (ET) includes the JAK2 -, CALR-, and MPL-mutated subtypes, and a triple-negative (TN) ET subtype, which lacks these canonical drivers." (PMID 41268701, 2025). "The majority of patients with essential thrombocythemia (ET) show somatic mutations of JAK2, CALR, or MPL." (PMID 40190073, 2025). "Most of essential thrombocythemia (ET) patients have the clone harboring a mutation in one of the JAK2, CALR, or MPL gene, and these clones generally acquire additional mutations at transformation to acute myeloid leukemia (AML)." (PMID 38987297, 2024). "JAK2 mutations are found in both polycythemia vera (PV) and essential thrombocythemia (ET), which are distinct but overlapping MPNs characterized by increased numbers of red blood cells and platelets, respectively." (PMID 38233595, 2024). "Polycythemia vera (PV) and essential thrombocythemia (ET) are diseases driven by canonical mutations in JAK2, CALR, or MPL gene." (PMID 37671053, 2023). "MPL codon p.W515 and p.S505N variants are associated with essential thrombocythemia (ET) and myelofibrosis (MF) in JAK2 p.V617F‐negative patients." (PMID 38058281, 2023). "Essential thrombocythemia (ET) is a myeloproliferative neoplasm resulting from driver gene mutations in JAK2, CALR, and MPL in hematopoietic stem cells." (PMID 35624199, 2022). "Somatic CALR mutations occur in approximately 70% of patients with JAK2 V617F-negative essential thrombocythemia (ET) and primary myelofibrosis (PMF)." (PMID 36359414, 2022). "A 71-year-old Japanese male was diagnosed with essential thrombocythemia (ET) with the JAK2 V617F mutation variation, in April 2011." (PMID 34552800, 2021). "And, in the10 years since the discovery of JAK2 mutations in MPNs, these lesions can be diagnostic of polycythemia vera (PV), essential thrombocythemia (ET), or primary myelofibrosis (PMF) in the appropriate clinical contexts." (PMID 26126599, 2015). "The importance of Tpo, its receptor and proximal signaling pathways in platelet function is illustrated by the discovery of gain-of-function mutations in Tpo, Mpl and Jak2 that all result in Essential Thrombocythemia (ET)." (PMID 24086539, 2013).
essential thrombocythemia (continued). "A 62-year-old woman was initially diagnosed with essential thrombocythemia (ET) on the basis of bone marrow aspirate and trephine at age 36 (November 1986), which was later proven to be Janus kinase 2 V617F mutation (JAK2) positive." (PMID 23476834, 2013). "A JAK2 mutation can be found in almost all patients with PV and approximately 50 percent of patients with essential thrombocythemia (ET) or PMF." (PMID 23606974, 2013). "Third, we still miss information in some diseases such as essential thrombocythemia (ET), in which JAK2 mutations are found in only half the cases, and TET2 mutations in less than 10%." (PMID 22823977, 2012). "Further, the V617F mutant of JAK2 is the causative mutation in approximately 50% of patients with the myeloproliferative disorder, essential thrombocythemia (ET), which is characterized by an increase in platelet count [11−13]." (PMID 19619605, 2009). "A woman in her 60s with a known history of JAK2-positive essential thrombocythemia presented with a one-week history of jaundice." (PMID 41799793, 2026). "CALR mutations, characteristic of essential thrombocythemia and primary myelofibrosis, represent a significant group of MPN cases and, compared with other mutations such as JAK2 or MPL, show distinct clinical and prognostic features." (PMID 39960584, 2026). "We report the case of a 76-year-old man with JAK2-positive essential thrombocythemia (ET) who developed persistent, intensely pruritic maculopapular skin lesions initially diagnosed as dermatitis." (PMID 41635379, 2026). "Essential thrombocythemia (ET) is a chronic myeloproliferative neoplasm (MPN) defined by sustained thrombocytosis, JAK2 V617F mutation in most cases, and elevated risks of thrombosis, bleeding, and secondary malignancies." (PMID 40672006, 2025). "We previously identified the JAK2-R1063H germline variant, which contributes to hereditary MPN and increased disease severity in essential thrombocythemia." (PMID 40841769, 2025). "Notably, patients with essential thrombocythemia, particularly those carrying the JAK2 V617F mutation, may have an increased risk of HIT-associated thrombosis, highlighting the potential synergistic effect of essential thrombocythemia and HIT in promoting extensive thrombotic complications." (PMID 41450710, 2025). "CALR mutations have been described essentially in JAK2 and MPL wild-type essential thrombocythemia and primary myelofibrosis." (PMID 38596359, 2024). "The subsequent sequence analysis of genomic DNA identified the JAK2 V617F mutation, leading to the diagnosis of an MPN, likely essential thrombocythemia." (PMID 39877786, 2024). "or essential thrombocythemia (n = 82; platelet count (PLT) = 675 ± 225 × 109 l−1 mean ± s.d., 51 with JAK2-V617F, 25 with CALR and 6 with MPL mutations)." (PMID 37620601, 2023). "The major clinical entities are represented by polycythemia vera (PV), essential thrombocythemia (ET), and primary myelofibrosis (PMF), that are caused by driver mutations affecting JAK2, MPL or CALR." (PMID 36499582, 2022). "Significant genetic associations included JAK2 V617F for immune thrombocytopenic purpura (p = 1.24 × 10−13) and a novel CALR loss of function variant for essential thrombocythemia (p = 1.59 × 10−13)." (PMID 35945607, 2022). "This disparity may be explained by that JAK2V617F expression in our study was more consistent with heterozygous JAK2V617F mutation in essential thrombocythemia (ET) patients because endogenous JAK2 gene was still present." (PMID 33664283, 2021). "Thirty-eight patients were classified as essential thrombocythemia of which 52.6% showed JAK2 V617F, 18.4% demonstrated CALR type 1, 7.9% denoted CALR type 2 and there was no mutation reported in 21.1%." (PMID 33936230, 2021). "Essential thrombocythemia (ET) is comprised among chronic myeloproliferative neoplasms (MPN) and is caused by driver mutations in JAK2, CALR, and MPL, which lead to megakaryocyte proliferation and prominent thrombocytosis." (PMID 32425934, 2020).
essential thrombocythemia (continued). "The risk of thrombosis is higher in JAK2 mutated PMF compared to CALR mutated PMF, despite the fact that calreticulin mutated patients display higher platelet counts, both in essential thrombocythemia and in PMF." (PMID 33255170, 2020). "Mutations of CALR have been reported primarily in wild-type JAK2 and MPL-related essential thrombocytosis (ET) and primary myelofibrosis (PMF)." (PMID 32000382, 2020). "This neoplasm is etiologically linked to a somatic mutation in the JAK2 gene (JAK2V617F), which is found in about 90% of patients with PV, and in about 50% of essential thrombocythemia (ET) and primary myelofibrosis (MF)." (PMID 31064135, 2019). "There is a need to study greater number of cases from different hematology clinics to describe the exact frequency of JAK2 in cases with primary thrombocytosis from Turkey." (PMID 29732039, 2018). "Forty-four MCAS patients had additional associated hematologic neoplasms, most frequently multiple myeloma, JAK2-positive essential thrombocytosis, and chronic lymphocytic leukemia." (PMID 29225779, 2017). "Janus kinase 2 (JAK2) and calreticulin (CALR) constitute the two most frequent mutations in essential thrombocythemia (ET), and both are reported to be mutually exclusive." (PMID 27486987, 2016). "Calreticulin (CALR) and JAK2-V617F gene mutations, which are major genetic mutations in patients with primary myelofibrosis (PMF) and essential thrombocythemia (ET), exert different effects on the clinical features and outcomes of these diseases." (PMID 27504244, 2016). "More than 95% of polycythemia vera (PV), and up to 50% of essential thrombocythemia (ET) and primary myelofibrosis (PMF) patients harbour the JAK2 V617F mutation 5–6." (PMID 24251790, 2013). "Genetic testing identified a somatic JAK2 V617F mutation (allelic frequency of 17%), consistent with essential thrombocythemia; no other mutations were detected, including no detectable BCR::ABL1 gene." (PMID 41552126, 2025). "While the JAK2 mutation is not exclusive to PV, it is also present in a significant proportion of patients with essential thrombocythemia and primary myelofibrosis." (PMID 39371836, 2024). "For JAK2, JAK2V617F is the most common mutation that is implicated in Philadelphia-negative myeloproliferative neoplasms (MPNs), and this covers polycythemia vera (PV), essential thrombocythemia (ET), and primary myelofibrosis (PMF)." (PMID 39682303, 2024). "Extensive splanchnic vein thrombosis with a completely occluding thrombus in the main portal vein, superior mesenteric vein and splenic vein precipitated spontaneous bacterial peritonitis in a non‐cirrhotic 44‐year‐old female with JAK2 V617 positive essential thrombocythemia." (PMID 37405042, 2023). "In 2018, the diagnosis of high-risk essential thrombocythemia (ET) (presence of the JAK2(V617F) mutation and advanced age without a history of thrombosis) was made." (PMID 36479156, 2022). "Further hematologic workup to rule out primary thrombocytosis included testing for Janus kinase 2 (JAK2) mutations, which came back negative." (PMID 35308660, 2022). "The test was negative for the BCR-ABL1 mutation, but the JAK2 V617F mutation was detected, meeting the criteria of essential thrombocythemia." (PMID 35756582, 2022). "Hereditary forms of primary thrombocytosis are caused by germline mutations within the genes encoding thrombopoietin (THPO), its receptor (MPL), and the receptor’s effector kinase Januskinase2 (JAK2)." (PMID 33712866, 2021). "Some patients with JAK2 V617F-positive essential thrombocythemia are asymptomatic, but others may develop hemorrhagic or thromboembolic complications." (PMID 32685224, 2020). "Atypical (asymptomatic) myocardial infarction with mild thrombocytosis may be the first clue for possible essential thrombocythemia with JAK2 V617F." (PMID 32685224, 2020). "In contrast, patients with JAK2-first disease were more likely to have essential thrombocytosis." (PMID 31784538, 2019).
essential thrombocythemia (continued). "This has been documented in essential thrombocythaemia where JAK2 V617F positive patients have a higher rate of thrombosis and in clonal haematopoiesis of indeterminate potential where the presence of mutated JAK2 is associated with an increased risk of coronary artery disease." (PMID 30574023, 2018). "In this work we study the feasibility of using HRM for the detection of CALR mutation in a series of patients with essential thrombocythemias and persistent thrombocytosis without mutations in JAK2 and MPL." (PMID 25068507, 2014). "For example, previous work on JAK2 was based on 92 haplotypes that were presumed tagged by individual SNPs, including one SNP that tagged the JAK2 46/1 haplotype and correlated with essential thrombocythemia." (PMID 22811759, 2012). "These disorders, which include polycythemia vera (PV), essential thrombocythemia (ET), and primary myelofibrosis (PMF), are driven by acquired somatic mutations in genes such as JAK2, CALR, or MPL, leading to hyperactivation of the JAK/STAT signaling pathway." (PMID 40646529, 2025). "They described a 74-year-old individual with JAK2+ essential thrombocythemia (ET) who presented with a left arm hematoma followed by a right forearm hematoma with compartment syndrome." (PMID 40636934, 2025). "Suspicious of essential thrombocythemia, genomic DNA analysis of the peripheral blood sample showed no pathogenic mutations regarding Janus kinase-2 (JAK2) V617F, JAK2 exon 12, calreticulin (CALR) exon 9, and myeloproliferative leukemia virus oncogene (MPL) W515L/K." (PMID 40385891, 2025). "Essential thrombocythemia (ET) is one of the classical Philadelphia-negative myeloproliferative neoplasms with different mutations that can be associated with it, like Janus kinase 2 (JAK2), myeloproliferative leukemia protein (MPL), and Calreticulin (CALR) (types 1 and 2)." (PMID 36788855, 2023). "In a variable percentage, patients with essential thrombocythemia show none of the known driver-gene mutations that may occur on JAK2, CALR, and MPL genes." (PMID 36135321, 2022). "Importantly, a bone marrow biopsy of the patient showed essential thrombocythemia (TE) with JAK2 mutation, all of which are involved in thrombosis but not ECD itself." (PMID 35687294, 2022). "A single nucleotide mutation of the janus kinase 2 gene (JAK2 V416F) is the most frequent among MPN driver mutations, occurring in more than 90% of patients with Polycythemia vera (PV) and about 50% of patients with Essential thrombocytosis (ET) and Primary myelofibrosis (PMF), respectively." (PMID 31921218, 2019). "Although essential thrombocythemia (ET) and immune thrombocytopenia (ITP) have different etiologies, 3 previous reports have described ET development in ITP patients, all of whom were positive for the JAK2 V617F mutation." (PMID 31689837, 2019). "In contrast, most studies agreed that platelet count apparently did not correlate with the risk of thrombosis in patients with essential thrombocythemia except the patients with the basis of age above 60 years, cardiovascular risk factors, thrombosis history and the presence of JAK-2 mutation." (PMID 29179528, 2017). "In the presence of a pathogenetic mutation in JAK2 or MPL, a differential diagnosis of essential thrombocythemia (ET) from reactive causes is relatively simple." (PMID 22997499, 2012). "These hematologic malignancies, typified by clonal proliferation of myeloid lineage cells, include polycythemia vera (PV), essential thrombocythemia (ET), and primary myelofibrosis (PMF or MF), which are variably associated with mutations in the Janus Kinase 2 (Jak2) gene." (PMID 41226376, 2025). "A subset of essential thrombocythemia (ET) cases are negative for disease-defining mutations on JAK2, MPL, and CALR and defined as triple negative (TN)." (PMID 34489506, 2021).